CRP (C-reactive protein)
Diseases named in the same sentence as CRP in open-access papers (continued):
Sharing a sentence is not in itself a finding about the gene and the disease.
tumor (continued). "Chemo-immunotherapy-treated patients displayed a significant multivariate influence of ECOG, CRP and PD-L1 on PFS and of ECOG, presence of a targetable genetic tumor alteration and CRP on OS." (PMID 35008255, 2021). "Our results showed that patients with elevated serum CRP levels tended to have more immunosuppressive TAM and TAN infiltrates, which are important contributors to the tumor-promoting milieu and facilitate tumor progression." (PMID 35070979, 2021). "Therefore, small-sized tumor, high level of CRP, and good tumor biology may be the causes of false-negative PET findings." (PMID 34678895, 2021). "The CRP levels increase with age (P = 0.01), as well as the advancement of the FIGO stage (P < 0.001), higher tumor grade (P = 0.012), and myometrial invasion (P < 0.001)." (PMID 32977765, 2020). "Right-sided tumours, pT4, node positivity (except pN1c), LNR, postoperative CEA, and CRP correlated with increased hazard of mortality when adjusting for baseline variables." (PMID 31893351, 2020). "Additionally, CRP may promote tumor growth protecting tumor cells from drug-induced apoptosis." (PMID 32182693, 2020). "C-reactive protein (CRP) is synthesised in hepatocytes—for instance, during infectious processes and following tissue trauma or neoplasia." (PMID 33266181, 2020). "Different biomarkers, such as circulating tumor DNA, circulating tumor cells, cytokines, exosomes and factors such as lactate dehydrogenase (LDH) and C-reactive protein (CRP) can be analyzed using liquid biopsies." (PMID 32793228, 2020). "In addition, tumor growth might lead to visceral tissue inflammation and increased CRP levels." (PMID 32104193, 2020). "Additionally, CRP may promote tumor growth by protecting tumor cells from apoptosis." (PMID 33023215, 2020). "A scoring system (“ACKT”) based on the variables of age, preoperative C-reactive protein (CRP) value, Karnofsky performance scale and tumor size supports prediction of postoperative PMV (sensitivity 73%, specificity 84%)." (PMID 33396290, 2020). "Univariate analyses indicated that several clinical indexes, such as vessel invasion, perineural invasion, tumor length, TNM stage, CRP, ALB, NLR, LDH and GRIm-Score, were significant predictors of CSS." (PMID 32047540, 2020). "Macrophages and adipocytes produce pro-inflammatory factors, resulting in elevated concentrations of circulating tumour necrosis factor-α (TNF-α), interleukin-6 (IL-6) and C-reactive protein (CRP), which are beneficial for tumour growth." (PMID 32210471, 2020). "Recently, the combination of CRP and albumin has been used to develop the Glasgow prognosis scoring system (GPS) for the study of tumor prognosis." (PMID 31965045, 2020). "Laboratory data revealed the C-reactive protein (CRP) level was 166 mg/L, tumor markers such as neuron-specific enolase (NSE) and ferroprotein (FER) were slightly abnormal." (PMID 31924167, 2020). "Serum elevation of C-reactive protein (CRP), an acute-phase protein, has been shown to be a prognostic indicator in a variety of neoplasms." (PMID 33028394, 2020). "In unadjusted analyses, pT3-subclassification, pN-subclassification, LNR, tumour deposits, elevated postoperative CEA, and preoperative CRP correlated with recurrence." (PMID 31893351, 2020). "Herein, we also assessed a wide array of systemic inflammatory markers, including LDH, CRP, SII, GPS, PI, PNI, as well as several tumor markers, including CEA, CA125, and CA199." (PMID 32898339, 2020). "The diagnostic specificity for CXCR4 levels (69%) was higher than that for CXCR2 (66%) and the classical tumor marker (CEA–47%), but lower in comparison to CRP levels (94%), similarly to the predictive value for positive (PV+ve) results." (PMID 32867211, 2020). "Serum PCT, CRP and LDH levels were positively correlated with tumour progression; LDH had the highest and PCT the lowest correlation." (PMID 30976022, 2019).
tumor (continued). "Baseline, highest and latest value of c-reactive protein (CRP), bilirubin and lactate dehydrogenase (LDH), as well as the tumor markers CA 19–9 and CEA, were examined." (PMID 31888547, 2019). "LDH had the highest correlation with tumour progression, whereas PCT had the lowest (LDH, r = 0.684; CRP, r = 0.570; PCT, r = 0.322)." (PMID 30976022, 2019). "Serum PCT, CRP and LDH levels were positively correlated with tumour progression (PCT, r = 0.322, P = 0.000; CRP, r = 0.570, P = 0.000; LDH, r = 0.684, P = 0.000); LDH had the highest and PCT the lowest correlation." (PMID 30976022, 2019). "Propensity score matching (PSM) was performed to reduce the selection bias between patients with low CRP (≤ 5.0 mg/mL) and those with high CRP (> 5.0 mg/mL) levels based on age, tumor-lymph node-metastasis (TNM) stage, and tumor grade." (PMID 31533862, 2019). "ROC analysis was further applied to evaluate the therapeutic efficiencies of TrxR activity as well as existing GC tumor biomarkers CEA, CA72-4, CA19-9 to differentiate between CRP and CUP group." (PMID 31836775, 2019). "Using linear and logistic regression models, we found that C-reactive protein and PLR on single variables, were statistically significantly related to the tumour parameters." (PMID 30662766, 2019). "Univariate survival analysis revealed that the preoperative CRP levels, TNM stage, tumor grade, drinking history, and anastomosis method were prognostic factors for overall survival (OS)." (PMID 31533862, 2019). "In the univariate analysis of OS and DFS, the significant prognostic parameters are tumor size, TNM stage, treatment exposure, serum AFP level, serum CRP level, serum albumin level, albumin / CRP ratio, and platelet / CRP ratio." (PMID 31164099, 2019). "When LDH and CRP were combined to diagnose tumour progression, the parallel method was also better, and the optimal cutoff was 295 U/L and 10 mg/L for LDH and CRP, respectively." (PMID 30976022, 2019). "According to our knowledge, the present study is the first to compare the diagnostic characteristics of CXCL-8 with the well-established tumor markers (CEA and SCC-Ag) and the marker of inflammation—CRP in the sera of OC patients." (PMID 30820705, 2019). "In the multivariate analysis, the results indicated that tumor size, TNM stage, treatment exposure, serum AFP level, and albumin / CRP ratio were independent factors for HCC prognosis." (PMID 31164099, 2019). "Our observations are also confirmed by a positive correlation between MDA and CEA/CRP levels, as well as between MDA and depth of tumour invasion in CRC patients." (PMID 31652642, 2019). "The largest tumor diameter (p = 0.008), ALP (p = 0.008), platelet (p < 0.001), and CRP (p = 0.005) in high PLR group were higher than those in low PLR group." (PMID 30961549, 2019). "Pre-RT pain was more prevalent in patients with AA or HW race/ethnicity, BMI ≥ 30 kg/m2, HER2-positive tumor, received trastuzumab alone or taxane+trastuzumab, received ALND, or pre-RT CRP ≥ 10 mg/L, compared to their respective comparison groups." (PMID 31138314, 2019). "The prognostic values of age, sex, smoking, T stage, N stage, TNM stage, tumor size, serum CRP level, NLR, PLR, maximum SUV, metabolic tumor volume, total lesion glycolysis, BM SUV, and BLR were assessed in the survival analysis." (PMID 31382679, 2019). "The largest tumor diameter (p = 0.048), ALP (p = 0.047), neutrophil percentage (p < 0.001), and CRP (p = 0.043) of patients in high NLR group were higher than those in low NLR group." (PMID 30961549, 2019). "On multivariate analysis controlling confounding factors, ferritin (P = 0.041), CRP (P = 0.010), ECOG-PS (P = 0.010), and tumor type (P = 0.018) were identified as independent prognostic factors for survival." (PMID 29879960, 2018). "Univariate analysis demonstrated that age, the Fuhrman grade, pT status, pN status, tumour thrombus, the NLR, the CRP/Alb and the PLR were significant predictors for both DFS and OS in Xp11.2 tRCC patients." (PMID 29890986, 2018).
tumor (continued). "Based on the results of univariate analyses, ECOG-PS, tumor type, prior treatment, serum ferritin, Hb, total bilirubin, γ-GT, albumin, WBC, and CRP significantly affected OS." (PMID 29879960, 2018). "It is reported that the GBM-secreted inflammatory cytokine interleukin (IL)-6 acts on liver cells, inducing them to secrete high levels of CRP, which reaches the GBM tumor through the blood circulation and is accumulated in tumor tissues." (PMID 29513714, 2018). "Within tumor tissue alone, MUC1 and KIT exhibited increased expression in patients with a low CRP compared to those with a CRP ≥5 mg/L." (PMID 30016964, 2018). "We also analysed if serum levels of the tumor markers (CA19-9 and CEA) or inflammatory markers (CRP and leucocyte count) were altered between patients with different T-, N- or M-status (according to UICC TNM classification, 7th edition 201030)." (PMID 29208940, 2017). "In univariate analysis, levels of AST, ALB, ALP, CRP, AFP, and NLR, tumor size, tumor number, metastasis, vascular invasion, antiviral therapy, and TACE with H101 were significantly associated with OS." (PMID 28728568, 2017). "Serum alpha-fetoprotein (AFP), hyper-sensitive C-reactive protein (hs-CRP), incomplete tumor encapsulation, and double positive staining of Cytokeratin 7 and Cytokeratin 19 on tumor cells were identified as independent predictors for OS." (PMID 28296727, 2017). "It is interesting that patient 14 experienced a significant increase in CRP, IL-6, and TNF-α level, but a significant decrease in tumor marker CEA levels." (PMID 29268708, 2017). "Other significant prognostic parameters included the CRP, AST, ALB, ALP, GGT, and AFP levels, the tumor diameter and vascular invasion." (PMID 28355305, 2017). "Tumor CTLA-4 expression was a significant prognostic factor for D-FFS (p = 0.044), and the UICC and CRP level were also significant prognostic factors (p < 0.001 and p = 0.005, respectively)." (PMID 26918337, 2016). "Activated SIR interrelates increased c-reactive protein, circulating neutrophils, NLR, mGPS, IL-6, platelets, tumor necrosis and decreased albumin, lymphocytes, hemoglobin, peritumoral infiltrate, and of course poorer survival." (PMID 27992611, 2016). "The univariate analysis indicated that tumor site (P = 0.022), Enneking’s surgical staging (P = 0.000), occurrence of metastasis (P = 0.000), GPS (P = 0.000), CRP (P = 0.000), NLR (P = 0.000), PLR (P = 0.030) and LMR (P = 0.020) were associated with OS." (PMID 28008988, 2016). "Increasing evidence of the prognostic value of preoperative CRP, albumin, and GPS support their utility for clinical decision-making in evaluation of postoperative survival, possibly combined with tumour markers." (PMID 27632196, 2016). "In this study, the value of the serum tumor markers CA19.9, CEA, CRP, albumin, IGF-1 and IGFBP3 alone or in combination, in the differential diagnosis of PDAC and CP was assessed." (PMID 26808421, 2016). "The NI calculation has the advantage of including not only CRP as a measure of systemic disease but also TK1, which is tumor-specific." (PMID 27747218, 2016). "The clinicopathologic variables, specifically tumor stage, tumor size, nodal metastasis, vascular invasion, CA19-9 level, administration of postoperative chemotherapy, and serum CRP levels, were tested in the multivariate analyses." (PMID 27733196, 2016). "In univariate analyses, tumor length (P =0.029), vessel invasion (P =0.011), TNM stage (P < 0.001), CRP/PNI ratio (P <0.001), GPS (P <0.001), CRP (P <0.001), PNI (P =0.002), NLR (P <0.001) and PLR (P <0.001) were significant predictors of CSS." (PMID 27557504, 2016). "The percentages of elevated results (diagnostic sensitivity) of CXCR4 (80%) were higher than those of CXCL12 (47%) and much higher than classical tumor markers—CEA (22%) and SCC-Ag (14%) as well as CRP (57%)." (PMID 27041792, 2016).
tumor (continued). "Under different inflammation states, proinflammatory cytokine intensity, in addition to tumor stage, independently predicted PFSR in patients with CRP <5 mg/L, whereas tumor stage was the only independent predictor of PFSR in patients with CRP ≥5 mg/L." (PMID 26799163, 2016). "Again, tumor size, TNM stage, Child-Pugh class and laboratory findings, such as AFP and Hs-CRP remained significant OS predictors." (PMID 25970775, 2015). "Common clinicopathologic parameters included with CRP were: stage (TNM, Dukes, others) 23% (59/256); metastasis (lymph node, liver, others) 17%; performance status (ECOG, KPS, others) 16%; tumor characteristics (histology, site, diameter, size) 16%; WBC 13%." (PMID 26717416, 2015). "In contrast to the close correlation between serum CRP level and unfavorable tumor factors, as shown in previous study, the elevated serum CRP level itself is not directly linked with these unfavorable tumor factors, such as maximal tumor size and tumor numbers, in the current analysis." (PMID 25602444, 2015). "We also found that the histologic grades of tumours correlated with CA125, CA15-3, CRP, and D-D Concentrations, however, only CRP and D-D elevations were seen in patients with metastatic or recurrent tumours." (PMID 26107255, 2015). "The fact, that CRP serum levels were only associated with the tumor size but not with other clinico-pathological parameters underlines the hypothesis, that CRP might provide additional prognostic information and does not only reflect other established prognostic parameters." (PMID 26248232, 2015). "Interestingly, neither tumor stage nor histologic grading was associated with high CRP levels." (PMID 26248232, 2015). "Besides, CRP may promote tumor growth in chronic inflammation." (PMID 25999661, 2015). "A Spearman correlation analysis further demonstrated that plasma D-dimer levels correlated with age, serum CRP level, LDH level, EBV DNA level, tumour TNM stage, and distant metastasis." (PMID 25109220, 2014). "After extensive univariate analysis, only significant variables (CEA, tumor diameter, NLR, neutrophil count, and CRP) were included in the multivariable logistic regression models." (PMID 25406793, 2014). "Further, using the means of covariate (tumor number, Choi response, MELD score and ln (CRP)) of the whole patients in this study showed by SPSS, the mean risk score 2.6 of this cohort can be calculated according to the formula." (PMID 24367506, 2013). "With multivariate analysis, the present study revealed Child-Pugh class, tumor size, tumor multiplicity, presence of PVT, AFP, CRP and NLR as independent factors predictive of outcome of HCC." (PMID 23409924, 2013). "With significant inter-correlations, levels of CRP and NLR escalated with aggravating Child-Pugh class from A to C or progressing tumor stage from I to IV." (PMID 23409924, 2013). "The relationship of CRP and NLR with Child-Pugh class and tumor characteristics, which were the two major determinants of the prognosis of patients with HCC, were evaluated." (PMID 23409924, 2013). "The significant prognostic role of CRP and NLR is supported by the evidence that the levels of both markers displayed a linear relationship with the progressing stage of tumor and Child-Pugh classification, known as the two key prognostic factors for HCC." (PMID 23409924, 2013). "In summary, this study demonstrated that CRP and NLR are not only markers of inflammation, but also independent prognostic indicators for HCC, reflecting tumor burden and hepatic reserve." (PMID 23409924, 2013). "When variables with univariate significance were introduced into in a multivariate model, the tumor response for Choi criteria, MELD score, the number of lesions, and serum CRP level were selected as independent prognostic predictors of survival." (PMID 24367506, 2013).
tumor (continued). "Then, we looked at the association between survival and clinical parameters including age, etiology, the largest size of tumor, the number of lesions, serum markers such as bilirubin, creatinine, INR, CRP, albumin, and AFP." (PMID 24367506, 2013). "CRP and NLR are independent indicators for survival in HCC patients, reflecting tumor burden and hepatic reserve." (PMID 23409924, 2013). "The multivariate analysis showed that the tumor response, the number of tumor nodules, MELD score and serum CRP levels independently determine the survival of these patients." (PMID 24367506, 2013). "Concentrations of CRP were significantly higher and concentrations of sCD26 were significantly lower in CRC patients compared with neoplasm-free participants (P<0.0001 and P=0.0003, respectively)." (PMID 22454079, 2012). "Serum VEGF concentrations were strongly correlated with some clinical variables: CRP, WBC, tumour size and stage of the disease." (PMID 23412843, 2012). "This manuscript details an analysis of these clinical data to determine if a correlation exists between IVC treatments, inflammation (measured by CRP, cytokine levels), and tumour progression (measured by PSA, CEA and other tumour markers)." (PMID 22963460, 2012). "There was correlation between tumor markers (PSA, CEA, CA27.29 and CA15-3) and changes in the levels of C-reactive protein." (PMID 22963460, 2012). "Our results regarding the differences in blood levels of CRP, sCD26 and TIMP-1 among CRC patients vs neoplasm-free participants are in line with those of several previous studies." (PMID 22454079, 2012). "C-reactive protein, sCD26 and TIMP-1 levels were found to be different in CRC patients compared with participants free of neoplasms." (PMID 22454079, 2012). "Laboratory findings demonstrated a leukocytes count of 11.4 × 109/L, an erythrocyte sedimentation rate of 30 mm/h, C reactive protein (CRP) level of 61.7 mg/L and normal serum tumor marker levels." (PMID 21672251, 2011). "After adjusting for tumour stage and age, both VEGF-A and CRP lost their predictive value and Ang-2 remained the only significant predictor of survival (model 2)." (PMID 21081932, 2011). "The CRP levels increased with tumour AJCC stage (P<0.001), T stage (P<0.001) and higher grade (P=0.004), as well as with increased tumour necrosis (P=0.002)." (PMID 21081932, 2011). "Although we cannot exclude this, the expected relations with factors like age, CRP, and history of CVD still support skin AF as a marker of AGEs." (PMID 21977038, 2011). "A study investigating the relationship between the serum levels of high sensitivity CRP (H-CRP) and the prognosis of HCC patients found positive H-CRP, albumin, tumor stage and initial treatment to be significant independent determinants of poor prognosis." (PMID 21176210, 2010). "On univariate survival analysis, sex (P=0.050), tumour stage (P=0.001), Fuhrman grade (P<0.001), UISS (P<0.001), C-reactive protein (P=0.002) were significant predictors of survival." (PMID 16523196, 2006). "There was an inverse relationship between percentage tumour CD4+ T-lymphocytes and C-reactive protein (rs=−0.245, P=0.003)." (PMID 15700032, 2005). "C-reactive protein is a non-specific inflammatory marker serving as an indicator of sensitivity and specificity in predicting tumour development." (PMID 41602421, 2026). "Brain SUVmean was independent of the radiomic features quantifying tumor involvement (r < 0.24, n = 380) and significantly correlated but complementary to several blood biomarkers including C-reactive protein (r = -0.37, n = 110 patients)." (PMID 41956561, 2026). "In the univariate analyses, several risk factors were identified: age, sex, BMI, ASA score, EBL > 30 mL, preoperative C-reactive protein, preoperative albumin, tumor size, T stage, and lack of duodenal stump reinforcement." (PMID 40507217, 2025).